PFDN1 (prefoldin subunit 1)
Description:
Binds specifically to cytosolic chaperonin (c-CPN) and transfers target proteins to it. Binds to nascent polypeptide chain and promotes folding in an environment in which there are many competing pathways for nonnative proteins.
Synonyms: PFD1; PDF
Tractability: Small molecule: a structure with a bound ligand is known. Antibody: the Human Protein Atlas places it where antibodies can reach. PROTAC: ubiquitination databases record sites on it; its protein half-life has been measured.
Gene: Protein-coding gene on chromosome 5 (140,245,035 to 140,303,113, reverse strand). Ensembl gene ENSG00000113068.
Subcellular location (Human Protein Atlas): Cytosol; Plasma membrane; Nucleoli
Pathways (Reactome):
Metabolism of proteins: Prefoldin mediated transfer of substrate to CCT/TriC
Gene Ontology:
Molecular function: amyloid-beta binding; protein binding; protein folding chaperone
Biological process: negative regulation of amyloid fibril formation; protein folding; protein stabilization
Cellular component: prefoldin complex; cytoplasm; protein folding chaperone complex
Genetic constraint (gnomAD): Loss-of-function variants: 2 observed, 2.16 expected, observed/expected ratio (o/e) 0.93, 90% interval 0.34 to 1.86. That is too few expected variants to judge how well the gene tolerates losing a copy. Missense variants: 14 observed, 17.84 expected, observed/expected ratio (o/e) 0.78, 90% interval 0.52 to 1.23. Synonymous variants: 11 observed, 5.37 expected, observed/expected ratio (o/e) 2.05.
Homologues: Orthologues: chimpanzee PFDN1 (99% identical), dog PFDN1 (99% identical), pig PFDN1 (99% identical), guinea pig PFDN1 (98% identical), rabbit PFDN1 (98% identical), mouse Pfdn1 (98% identical), rat Pfdn1 (98% identical), macaque PFDN1 (93% identical), zebrafish pfdn1 (78% identical), tropical clawed frog pfdn1 (76% identical), Drosophila melanogaster Pfdn1 (34% identical), Caenorhabditis elegans pfd-1 (32% identical).
Diseases named in the same sentence as PFDN1 in open-access papers:
PFDN1 is named in the same sentence as 13 diseases in open-access papers, as found by Europe PMC text mining. Sharing a sentence is not in itself a finding about the gene and the disease. The quoted sentences say what the papers report.
lung carcinoma (6 papers, 2017 to 2022). "Much evidence confirmed that high PFDN1 expression is associated with the metastasis and poor prognosis of gastric cancer, lung cancer, and colorectal cancer." (PMID 35111762, 2021). "FILIP1L knockdown and the resultant PFDN1 increase lead to increased mucin secretion and/or overexpression in mouse lung as well as lung cancer cells, possibly generating a niche for lung cancer progression through increased inflammation and fibrosis." (PMID 36860703, 2022). "Preliminary immunoblot experiments demonstrated that FILIP1L expression coincided inversely with PFDN1 protein levels in lung cancer cell lines." (PMID 36860703, 2022). "Thus, we examined the relationships between FILIP1L and PFDN1 expression in the context of lung cancer." (PMID 36860703, 2022). "PFDN1 has been proposed as a target for the treatment of lung cancer." (PMID 35111762, 2021). "The involvement of PFDN1 in promoting EMT in lung cancer suggests that PFDN accumulation may play an important role in the evolution of lung cancer and the onset of metastasis." (PMID 32344577, 2020). "Interestingly, PFDN1 has recently been shown to promote epithelial-mesenchymal transition and lung cancer progression." (PMID 28959263, 2017). "PFDN1 overexpression promotes epithelial–mesenchymal transition (EMT) and increases the growth of xenograft lung cancer (LC) cell lines." (PMID 32344577, 2020). "Overexpressed PFDN1 promotes EMT, xenograft tumor formation, and metastasis in lung cancer cells." (PMID 36860703, 2022).
colorectal cancer (4 papers, 2020 to 2024). A primary or metastatic malignant neoplasm that affects the colon or rectum. "PFDN1 may also be a diagnostic biomarker and potential candidate for the treatment of colorectal cancer." (PMID 35111762, 2021). "Moreover, the expression of PFDN1 was positively associated with tumor size and invasion in colorectal cancer (CRC)." (PMID 31957800, 2020). "Silencing of PFDN1 resulted in G2/M cell cycle arrest and cytoskeletal defects in colorectal cancer, leading to significant inhibition of cell proliferation and motility." (PMID 38612711, 2024). "Studies of PFDN1 in colorectal cancer have shown that PFDN1 is highly expressed in colorectal cancer compared to neighboring normal tissues." (PMID 38612711, 2024). "PFDN1 promotes the proliferation and metastasis of colorectal cancer by maintaining cytoskeletal proteins, particularly F-actin and α-tubulin." (PMID 35111762, 2021). "A study of PFDN1 mRNA and protein levels in clinical specimens from patients with colorectal cancer showed higher levels of PFDN1 in colorectal cancer samples, particularly the invasive form of the disease, compared with healthy tissues." (PMID 35111762, 2021).
colon cancer (3 papers, 2020 to 2022). "PFDN1 is overexpressed in multiple cancer types including lung, colon, and gastric cancer, and its overexpression is associated with poor prognosis in colon cancer and NSCLC." (PMID 36860703, 2022). "FILIP1L regulates proteasome-dependent degradation of PFDN1, and increased PFDN1, caused by downregulation of FILIP1L, drives mucin secretion in colon cancer." (PMID 36860703, 2022). "PFDN1 has been reported to be involved in the development of many types of tumors (such as lung, breast, and colon cancers)." (PMID 32699605, 2020). "We have recently shown that FILIP1L regulates proteasome-dependent degradation of the molecular chaperone PFDN1, and that increased PFDN1 expression, resulting from downregulation of FILIP1L leads to cytokinesis defects and enhanced tumor growth in colon cancer." (PMID 36860703, 2022).
gastric cancer (3 papers, 2020 to 2022). A primary or metastatic malignant neoplasm involving the stomach. "For example, in gastric cancer cells, PFDN1 activates alterations of the EMT through Wnt/β-catenin signaling." (PMID 35111762, 2021). "The silencing of PFDN1 decreased the expression of downstream proteins of Wnt/β-catenin signaling, suggesting that PFDN1 may be a specific target to attenuate the development of gastric cancer." (PMID 35111762, 2021). "Interestingly, upregulated PFDN1 was shown to activate Wnt/β-catenin signaling-mediated EMT that facilitates cell migration, invasion, and metastasis in gastric cancer." (PMID 36860703, 2022).
liver cancer (1 paper, 2022). An epithelial or non-epithelial malignant neoplasm that arises from the liver. "Based on these findings, PFDN1/2/3/4 were significantly associated with prognosis of patients with HCC, and these genes become useful biomarkers to predict the survival of liver cancer patients." (PMID 36438659, 2022). "Higher expression of PFDN1 (HR = 1.49, 95% CI: 1.05–2.10, p = 0.025), PFDN2 (HR = 1.49, 95% CI: 1.05–2.11, p = 0.024), VBP1 (HR = 1.47, 95% CI: 1.03–2.08, p = 0.031), and PFDN4 (HR = 1.78, 95% CI: 1.25–2.53, p = 0.001) was significantly associated with shorter OS of liver cancer patients." (PMID 36438659, 2022).
mucinous colorectal adenocarcinoma (1 paper, 2022). "In mucinous colorectal adenocarcinoma (MAC), PFDN1 is a direct target of filamin A interacting protein 1-like (FILIP1L) and is degraded by the proteasome." (PMID 36438659, 2022).
tumor (6 papers, 2020 to 2023). "Some literature studies have shown that the expression of PFDN1 positively correlates with tumor size and invasion." (PMID 37058032, 2023). "At the same time, silencing PFDN1 can lead to cell cycle dysfunction of G2amp M, which can inhibit tumor proliferation and movement." (PMID 37058032, 2023). "Our pertinent findings indicate that patients with PFDN5 overexpression in the tumor tissue had higher mortality rates, and those having PFDN1 overexpression also showed higher rates of recurrence, specifically for distant metastasis." (PMID 32344577, 2020). "PFDN1, 3, and 5 overexpression were found in 38% (n = 22), 53% (n = 31), and 41% (n = 24) of tumor samples." (PMID 32344577, 2020). "PFDN1, 3, and 5 overexpression (+++) was found in 38% (n = 22), 53% (n = 31), and 41% (n = 24) of tumor samples." (PMID 32344577, 2020). "Meanwhile, silencing PFDN1 also exhibits inhibitory effect upon tumor proliferation and motility due to G2/M cell cycle dysfunction." (PMID 31957800, 2020). "Intriguingly, our previous study demonstrates that the expression of PFDN1 positively correlates with tumor size and invasion." (PMID 31957800, 2020). "Moreover, overexpression of PFDN1 induces the tumor growth, metastasis, cellular invasion and epithelial–mesenchymal transition (EMT) of lung cancer." (PMID 31957800, 2020).
cancer (5 papers, 2020 to 2026). A tumor composed of atypical neoplastic, often pleomorphic cells that invade other tissues. "Recent investigations have uncovered abnormal overexpression of PFDN1 in various cancers, including colorectal, gastric, lung, and liver." (PMID 39238386, 2024).
PFDN1 also shares sentences with these, for which no sentence is quoted: non-small cell lung carcinoma (2 papers); breast invasive carcinoma (1); hepatocellular carcinoma (1); Nephroblastoma (1); prostate carcinoma (1).